SH2D3C (SH2 domain containing 3C)
Description:
Acts as an adapter protein that mediates cell signaling pathways involved in cellular functions such as cell adhesion and migration, tissue organization, and the regulation of the immune response. Plays a role in integrin-mediated cell adhesion through BCAR1-CRK-RAPGEF1 signaling and activation of the small GTPase RAP1. Promotes cell migration and invasion through the extracellular matrix. Required for marginal zone B-cell development and thymus-independent type 2 immune responses (By similarity). Mediates migration and adhesion of B cells in the splenic marginal zone via promoting hyperphosphorylation of NEDD9/CASL (By similarity). Plays a role in CXCL13-induced chemotaxis of B-cells (By similarity). Plays a role in the migration of olfactory sensory neurons (OSNs) into the forebrain and the innervation of the olfactory bulb by the OSN axons during development (By similarity). Required for the efficient tyrosine phosphorylation of BCAR1 in OSN axons (By similarity). [Isoform 1]: Important regulator of chemokine-induced, integrin-mediated T lymphocyte adhesion and migration, acting upstream of RAP1 (By similarity). Required for tissue-specific adhesion of T lymphocytes to peripheral tissues (By similarity). Required for basal and CXCL2 stimulated serine-threonine phosphorylation of NEDD9 (By similarity). May be involved in the regulation of T-cell receptor-mediated IL2 production through the activation of the JNK pathway in T-cells (By similarity). [Isoform 2]: May be involved in the BCAR1/CAS-mediated JNK activation pathway.
Synonyms: SHEP1; NSP3; CHAT; PRO34088
Tractability: Antibody: UniProt places it where antibodies can reach, with high confidence; its Gene Ontology location is reachable by antibodies, with medium confidence. PROTAC: ubiquitination databases record sites on it; its protein half-life has been measured.
Gene: Protein-coding gene on chromosome 9 (127,738,317 to 127,778,727, reverse strand). Ensembl gene ENSG00000095370.
Subcellular location: Cytoplasm; Cell membrane; Cell projection, axon; Cell projection, ruffle membrane; Cell membrane (Isoform 1)
Subcellular location (Human Protein Atlas): Cytosol
Gene Ontology:
Molecular function: protein binding; guanyl-nucleotide exchange factor activity; phosphotyrosine residue binding
Biological process: cell adhesion; JNK cascade; small GTPase-mediated signal transduction
Cellular component: cytoplasm; cytosol; plasma membrane; protein complex involved in cell adhesion; axon; ruffle membrane
Genetic constraint (gnomAD): Loss-of-function variants: 24 observed, 64.96 expected, observed/expected ratio (o/e) 0.37, 90% interval 0.27 to 0.52. The upper end of that interval is the gene's LOEUF score, 0.52, which puts it in group 2 of 6, group 1 being the genes least tolerant of losing a copy. Missense variants: 908 observed, 1,131.2 expected, observed/expected ratio (o/e) 0.8, 90% interval 0.76 to 0.85. Synonymous variants: 439 observed, 459.85 expected, observed/expected ratio (o/e) 0.95, 90% interval 0.88 to 1.03.
Homologues: Orthologues: chimpanzee SH2D3C (99% identical), macaque SH2D3C (97% identical), dog SH2D3C (90% identical), rat Sh2d3c (86% identical), guinea pig SH2D3C (86% identical), pig SH2D3C (77% identical), mouse Sh2d3c (74% identical), tropical clawed frog sh2d3c (57% identical), zebrafish sh2d3ca (47% identical), zebrafish sh2d3cb (34% identical), Drosophila melanogaster CG9098 (28% identical). Paralogues in human: BCAR3 (38% identical), SH2D3A (24% identical).
Diseases named in the same sentence as SH2D3C in open-access papers:
SH2D3C is named in the same sentence as 35 diseases in open-access papers, as found by Europe PMC text mining. Sharing a sentence is not in itself a finding about the gene and the disease. The quoted sentences say what the papers report.
lung carcinoma (3 papers, 2021 to 2025). "NSP3 (SH2D3C) demonstrated a high predictive value and association with therapy resistance in lung cancer, hence serving as an attractive target for therapy exploration." (PMID 34829812, 2021). "In the present in silico study, we demonstrated that NSP3 (SH2D3C) is associated with advanced stage and poor prognoses of lung cancer cohorts." (PMID 34829812, 2021). "Interestingly, we found that NSP3 (SH2D3C) expression was inversely associated with CTL levels in lung cancer patients." (PMID 34829812, 2021). "This gene has been reported to be hypomethylated in acute lymphoblastic leukemia (ALL), the most common childhood blood cancer, while a recent study has identified SH2D3C as a prognostic biomarker of tumor progression and immune evasion for lung cancer." (PMID 38650628, 2024). "Collectively, these findings prove that hyper-methylation and copy number alterations of NSP3 (SH2D3C) are associated with infiltration of immune cells and poorer prognosis of lung cancer cohorts." (PMID 34829812, 2021). "Specifically, our differential expression and survival analyses strongly suggested that NSP3 (SH2D3C) is a potential biomarker of advanced stages of lung cancer." (PMID 34829812, 2021). "Collectively, our results suggest that NSP3 (SH2D3C) is associated with the advanced stage and poor prognosis of lung cancer and thus could serve as a prognostic biomarker of lung cancer progression and follow-up." (PMID 34829812, 2021). "Furthermore, we queried the differential protein expression levels of NSP3 (SH2D3C) between lung cancer tissue and disease-free tissue." (PMID 34829812, 2021). "In addition, lung cancer patients with high methylation levels of NSP3 (SH2D3C) exhibited shorter survival duration than cohorts with low methylation levels." (PMID 34829812, 2021). "Interestingly, we found that lung cancer tumors exhibited higher intensity of NSP3 (SH2D3C) than the pathological free tissue." (PMID 34829812, 2021). "Our correlation analysis suggested that NSP3 (SH2D3C) promotes tumor immune evasion via dysfunctional T-cell phenotypes and T-cell exclusion mechanisms in lung cancer patients." (PMID 34829812, 2021). "We evaluated the effect of CNA and methylation of NSP3 (SH2D3C) in lung cancer, and the results revealed that NSP3 (SH2D3C) is hypermethylated in tumors of lung cancer patients compared to the normal tissue." (PMID 34829812, 2021). "Altogether, our findings strongly suggest that NSP3 (SH2D3C) promotes tumor immune evasion via dysfunctional T-cell phenotypes and T-cell exclusion mechanisms in lung cancer patients." (PMID 34829812, 2021). "Genetic alterations of NSP3 (SH2D3C) co-occurred inversely with Epidermal Growth Factor Receptor (EGFR) alterations and elicited its pathological role via modulation of various components of the immune and inflammatory pathways in lung cancer." (PMID 34829812, 2021). "However, our focus is on lung cancer, and we found that NSP3 (SH2D3C) is expressed at a lower level in lung cancer tumors than the adjacent normal tissue." (PMID 34829812, 2021).
Alzheimer disease (2 papers, 2016 to 2023). A progressive, neurodegenerative disease characterized by loss of function and death of nerve cells in several areas of the brain leading to loss of cognitive function such as memory and language. "Recently, SH2D3C was found to be upregulated in rat cortical neurons after treatment with amyloid-ẞ-oligomers, and higher protein levels of SH2D3C were also detected in mice with Alzheimer’s disease compared with wild type." (PMID 37762480, 2023).
lung adenocarcinoma (1 paper, 2021). A carcinoma that arises from the lung and is characterized by the presence of malignant glandular epithelial cells. "However, mutation and multiple alterations were the only genetic alterations of NSP3 (SH2D3C) in lung adenocarcinoma cohorts." (PMID 34829812, 2021). "We used the cBioPortal database to query the genetic alteration profile of NSP3 (SH2D3C) in 566 lung adenocarcinoma cases (TCGA, PanCancer Atlas) and found that 2.1% of the cohorts harbored genetically altered NSP3 (SH2D3C)." (PMID 34829812, 2021).
melanoma (1 paper, 2024). A malignant, usually aggressive tumor composed of atypical, neoplastic melanocytes.
tumor (7 papers, 2021 to 2025). "On a contrary note, we found that cohorts with metastatic lung cancer exhibited higher NSP3 (SH2D3C) expression levels than the primary tumor." (PMID 34829812, 2021). "Our differential expression profile of NSP3 (SH2D3C) between tumor and adjacent normal tissue revealed that NSP3 (SH2D3C) has deregulatory expression in tumor samples of TCGA cancer types." (PMID 34829812, 2021). "In addition, other genes have been involved in cancer processes, such as interference with innate immune system (SH2D3C), apoptosis (BLCAP), crossing-over regulation during meiosis (RNF212), and tumor suppression (ZDHHC14, MIR138-2, and PHTF1)." (PMID 36535927, 2022). "In addition, we found that SCNA of NSP3 (SH2D3C) including deep deletion, arm-level deletion, arm-level gain, and high amplification also mediated the infiltrations of the tumor-immune cells in both LUAD and LUSC." (PMID 34829812, 2021).
cancer (4 papers, 2018 to 2022). A tumor composed of atypical neoplastic, often pleomorphic cells that invade other tissues. "As such, different therapeutic approaches must be considered when targeting NSP3 (SH2D3C) in different cancer types." (PMID 34829812, 2021). "Our results suggest that NSP3 (SH2D3C) is differentially expressed in different cancer types and thus could serve different prognostic purposes in different cancer types." (PMID 34829812, 2021). "These CNV regions encode nineteen known genes, and some of which have been shown to affect aging-related phenotypes such as the shortening of telomere length (ZNF208), the risk of cancer (FOXA1, LAMA5, ZNF716), and vascular and immune-related diseases (ARHGEF10, TOR2A, SH2D3C)." (PMID 29883365, 2018).
SH2D3C also shares sentences with these, for which no sentence is quoted: infection (115 papers); viral infection (44); COVID-19 (30); Rotavirus infection (5); SARS-CoV infection (4); osteosarcoma (3); co-infection (2); fragile X syndrome (2); hepatoma (2); acute lymphoblastic leukemia (1); acute myeloid leukaemia (1); Arthritis (1); asthma (1); blood cancer (1); bronchiolitis (1); diabetic cardiomyopathy (1); encephalomyelitis (1); glioblastoma (1); liver disease (1); macrophage activation syndrome (1); metastatic cancers (1); Middle East respiratory syndrome (1); multiple sclerosis (1); neurodegenerative disease (1); polyarthritis (1); renal carcinoma (1); Sepsis (1); vascular disorder (1); ZIKV infection (1).